STAT3 (signal transducer and activator of transcription 3)
Diseases named in the same sentence as STAT3 in open-access papers (continued):
Sharing a sentence is not in itself a finding about the gene and the disease.
ovarian carcinoma (continued). "In ovarian cancer cells, many survival pathways are persistently activated, including AKT, ERK, SRC and STAT3 signaling." (PMID 25928246, 2015). "In ovarian cancer, increased levels of EGF stimulate IL6 secretion, which promote the mobility and resistance to chemotherapy via the JAK/STAT3, SHP-2/Ras, MAPK, and PI3K/Akt signaling pathways." (PMID 26356073, 2015). "Our previous study has demonstrated that the constitutive phosphorylation of STAT3 is largely mediated through JAK1 in these ovarian cancer cells, suggesting a possibility of JAK1 as a main kinase responsible for activation of STAT3 by EGF blockade." (PMID 25928246, 2015). "Selective inhibitors of Wnt, Notch or STAT3 signaling were employed to treat OVCAR-3 and CAOV-3 cells to elucidate the significance of individual signaling pathways for ovarian cancers." (PMID 25896424, 2015). "In this study, two human ovarian cancer cell lines, OVCAR-3 and CAOV-3, were treated by 120 μM resveratrol and their responses to the treatment and the statuses of Wnt, Notch and STAT3 signaling in them were analyzed by multiple experimental approaches." (PMID 25896424, 2015). "We found that treatment of human ovarian cancer cells with an EGFR inhibitor, gefitinib, resulted in increased STAT3 phosphorylation in a dose- and time-dependent manner." (PMID 25928246, 2015). "Due to the advantages of decoy ODN and SLN, herein, we incorporated STAT3 decoy ODN into SLN to form SLN-STAT3 decoy ODN complexes and detected their characteristics as well as their uptake behavior in the human ovarian cancer cell lines SKOV3 and A2780." (PMID 25923701, 2015). "A number of pro-survival signaling pathways is persistently activated in human ovarian cancer, including the epidermal growth factor receptor (EGFR) and janus kinase/signal transducer and activator of transcripton 3 (JAK/STAT3) pathways." (PMID 25928246, 2015). "The inhibition of CD147, P-gp, and p-Akt by STAT3 decoy oligodeoxynucleotide (ODN) technology inhibits ovarian cancer cell invasiveness and enhances the paclitaxel sensitivity of SKOV3 and OVCAR3 ovarian cancer cells." (PMID 25268615, 2014). "We have recently demonstrated activation of the JAK2/STAT3 pathway and the enhancement of a cancer stem cell (CSC)-like phenotype in ovarian cancer cells treated in vitro with chemotherapeutic agents." (PMID 24782986, 2014). "Signal transducer and activator of transcription 3 (STAT3) is activated in majority of ovarian tumors and confers resistance to cisplatin treatment in patients with ovarian cancer." (PMID 22280969, 2012). "Our results also provide evidence that DIM inhibits the invasion of ovarian cancer cells and angiogenesis by inhibiting HIF-1α and VEGF, which are regulated by STAT3." (PMID 22280969, 2012). "The relationships between the observed activation of the JAK2/STAT3 pathway in ovarian specimens were correlated with EGF-induced phenotypic changes in OVCA 433 and SKOV3 ovarian carcinoma cell lines." (PMID 19088723, 2009). "Such activation of STAT3 suggests a rationale for a combination of anti-STAT3 and EGFR/IL-6R therapy to suppress the peritoneal spread of ovarian cancer." (PMID 19088723, 2009). "For instance, when paclitaxel was used to treat ovarian cancer cells derived from recurrent patient tumors, it triggered activation of the JAK2/STAT3 signaling pathway and led to elevated expression of CSC-associated genes and proteins in the cells that remained viable." (PMID 40430852, 2025). "Interestingly, miR-296-3p encapsulated by sEVs from CAFs has been shown to regulate intercellular communication and promote ovarian cancer development by affecting the PTEN/Akt and SOCS6/STAT3 signaling pathways." (PMID 40008006, 2025).
ovarian carcinoma (continued). "Additionally, melittin induces apoptosis in ovarian cancer cells by elevating the expression of DR3, DR4, and DR6 death receptors and inhibiting the JAK2/STAT3 signaling pathway." (PMID 38445441, 2024). "Resveratrol could counteract the IL6 induction of cell migration in ovarian cancer cells through the induction of autophagy in the cells at the migration front, paralleled by the up-regulation of ARH-I and down-regulation of STAT3 expression." (PMID 39766086, 2024). "To improve siRNA delivery and silence a model STAT3 gene, we hypothesized that oleyl acylation to CPPs, specifically (WRH)n, would enhance STAT3 silencing efficiency in breast and ovarian cancer cells." (PMID 39204188, 2024). "Resveratrol could counteract the IL6 induction of cell migration in ovarian cancer cells through the induction of autophagy in the cells at the migration front, paralleled by the up-regulation of ARH1 and down-regulation of STAT3 expression." (PMID 39766086, 2024). "IL-6 may facilitate ovarian cancer progression through additional pathways, such as IL-6/JAK2/STAT3, IL-6/STAT3/HIF-1α, and mtDNA/toll-like receptor (TLR9)/NF-κB/IL-6." (PMID 39061859, 2024). "It was shown that in ovarian cancer, miR-217 inhibits tumour-induced M2 macrophage polarisation by targeting IL-6 and regulating the JAK3/STAT3 signalling pathway and that in renal cell carcinoma, BMP-6 induces M2 polarisation through activation of the Smad5/STAT3 pathway by IL-10." (PMID 38143746, 2023). "Furthermore, the relationship between hyperactive EGFR signalling through STAT3 and PI3K activity together promotes high-grade ovarian cancer progression to cisplatin resistance." (PMID 37935712, 2023). "It has been demonstrated that SP600125 and LY294002 significantly decreased ovarian cancer cell adhesion to M-Met5A cells; however, the STAT3 inhibitor AG490 did not." (PMID 36766725, 2023). "Moreover, miR-222-3p from EOC (epithelial ovarian cancer) activates macrophages, leading to the formation of TAMs via the SOCS3/STAT3 pathway." (PMID 37605155, 2023). "ERK, STAT3, and p38 MAPK have also been found to regulate paclitaxel-induced chemosensitivity in many carcinomas, including lung cancer, gastric cancer, breast cancer, and ovarian cancer." (PMID 38137377, 2023). "•Inhibition of JAK2/STAT3 signaling pathway could reduce the effect of CHAF1A overexpression on the proliferation and growth of epithelial ovarian cancer cells." (PMID 37575547, 2023). "Taken together, RUNX1, as a very important STAT3 regulator, may act as a signal transduction factor through EGFR, which provides a theoretical basis for further understanding the roles of RUNX1 in ovarian cancer." (PMID 37760803, 2023). "ALDH1A2 suppresses the proliferation and migration of epithelial ovarian cancer cells by downregulating STAT3, and enhanced ALDH1A2-related signalling may provide new opportunities for therapeutic intervention in ovarian cancer." (PMID 36651035, 2023). "From this evidence, while the presence of OSM in ovarian cancer patients is not confounded, OSM-mediated STAT3 signaling does impact ovarian cancer progression." (PMID 37841259, 2023). "Similarly, hypoxic conditions enriched ovarian cancer cell exosomes for miR-21-3p, miR-125b-5p, and miR-181d-5p, which induced M2 polarization in culture through SOCS4/5/STAT3 pathways." (PMID 36248881, 2022). "Furthermore, exogenously added IL-6 was shown in a separate study to activate the JAK2/STAT3 pathway and promote migration in SKOV3 and OVCA433 ovarian cancer cell lines." (PMID 35565396, 2022). "STAT3 regulated the expression of HIF-1α, contributing to ovarian cancer angiogenesis." (PMID 36524006, 2022). "Among the targets regulated by miR-124, we could isolate at least six genes (PDCD6, ROCK1, SLUG, STAT3, TGF-β, ZEB1) common to several epithelial cancers, including lung, stomach, hepatocellular, breast, and ovarian cancers." (PMID 36362406, 2022).
ovarian carcinoma (continued). "In addition, TRIM47 enhanced STAT3 phosphorylation, and the knockdown of STAT3 attenuated the oncogenic role of TRIM47 in ovarian cancer." (PMID 36288633, 2022). "However, STAT3 knockdown abolished these effects, suggesting that TRIM47 is an oncogenic factor in ovarian cancer that at least in part exerts its activity through STAT3." (PMID 36288633, 2022). "RNA sequencing results revealed that disturbance of transcriptome was observed in shNTPCR ovarian cancer cells, and several miRNAs and TFs were predicted to be hub genes correlated with ovarian cancer, including hsa-miR-124-3p, hsa-miR-146a-5p, hsa-miR-30a-5p, EP300, GATA2, and STAT3." (PMID 34539736, 2021). "Exposing ovarian cancer cell lines to ERK 1/2, AKT and STAT3 inhibitors for 48 h, resulted in a significant change in SNAIL 1 and SNAIL 2 expression in all ovarian cancer cell lines, however, this effect depended on the kind of inhibited signaling protein, as well as on the type of cell line." (PMID 33478150, 2021). "In addition, CHRF contributes to cisplatin resistance of ovarian cancer cells by regulating EMT and STAT3 signaling via miR-10b." (PMID 34512721, 2021). "STAT3/p-STAT3 expression was significantly lower in patients with mucinous ovarian cancer than in patients with nonmucinous ovarian cancer (OR = 0.61, 95% CI = 0.42–0.87, p = 0.007)." (PMID 34789292, 2021). "We have previously demonstrated that constitutive activation of STAT3 was present in ovarian cancer cell lines but not in normal ovarian surface epithelial cells, making selective STAT3 inhibition an excellent candidate for ovarian cancer treatment." (PMID 33909625, 2021). "In addition, I-BET151 reduces the migration and invasion of EOC cells by inhibiting the Stat3 signaling pathway and downregulating ZEB2 and N-cadherin, which also inhibits tumor metastasis in the abdominal metastasis model of ovarian cancer." (PMID 34540687, 2021). "Finally, our data demonstrated that miR-146b overexpression resulted in a greater suppression of cell migration than STAT3 pathway inhibition alone.These results suggest a complex and heterogeneous role of EGFR in ovarian cancer." (PMID 34369236, 2021). "Norepinephrine and E induce STAT3 phosphorylation through ADRB2; STAT3 then translocates into the nucleus to activate target genes, leading to the proliferation, infiltration, and metastasis of ovarian cancer cells." (PMID 34307378, 2021). "STAT3 is a universal factor determining the expression of SNAIL1/2 in ovarian cancer cells regardless of their chemoresitance or invasive capabilities." (PMID 33478150, 2021). "The meta-analysis results suggested that ovarian cancer tissue had higher STAT3/p-STAT3 expression than that of normal tissue and borderline and benign tumours." (PMID 34789292, 2021). "In vivo studies also confirmed the role of STAT3 in the effect of FBP1 in ovarian cancer cells with or without cisplatin treatment." (PMID 34363022, 2021). "SC144 is an orally active, small molecule gp130 inhibitor with high potency against human ovarian cancers without toxicity to normal tissues, and this was achieved by binding to gp130 that abrogated subsequent STAT3 activation." (PMID 34149710, 2021). "The possibility of targeting CD44/STAT3 axis to boost the antitumor efficacies of PARP inhibitors and overcome PARP inhibitor resistance may lead to better treatment for ovarian cancer patients." (PMID 33335857, 2020). "The involved molecules, including ID1, STAT3, and ATF6, may have a potential to be targeted in combination with chemotherapeutic agents to improve ovarian cancer survival." (PMID 32080166, 2020).
ovarian carcinoma (continued). "The results showed that the exogenous overexpression of THOR could rescue the STAT3 phosphorylation and other downstream effectors expression in THOR-knockdown ovarian cancer cells." (PMID 32552789, 2020). "Moreover, CD83 functions through the activation of MAP3K7-MEK1/2-ERK1/2 cascades to further regulate downstream FOXO1/p21/CDK2/CCNB1 and STAT3/DKK1 signaling pathways, thus activating proliferation and spheroid formation of ovarian cancer cells, respectively." (PMID 32823589, 2020). "Concurrent activation of multiple signaling pathways, including JAK/STAT3, PI3K/AKT/mTOR, SRC, and MEK/MAPK, appears to be more common in ovarian cancer and might be the critical force that drives ovarian cancer cells to proliferate and survive." (PMID 32927828, 2020). "This underscores the concept that simultaneous blockade of multiple cell growth/survival pathways, including JAK/STAT3, PI3K/AKT/mTOR, SRC and MEK/MAPK, may be required to achieve maximum anti-tumor activity in patients with ovarian cancer." (PMID 32927828, 2020). "Specifically, activated STAT3 has been shown to induce matrix metalloproteinase 2 and 9 (MMP-2, MMP-9) expression in ovarian cancer models, which are important factors involved in the degradation of extracellular matrix necessary for tumor invasion and metastasis." (PMID 33335857, 2020). "And p-STAT3/NF-kB/IL-6 and VEGF is a cascade amplification loop in ovarian cancer." (PMID 32190078, 2020). "Indeed, under cisplatin treatment, CAFs promote the phosphorylation and activation of STAT3, which upregulates the levels of BCL-2 in ovarian cancer and in lung adenocarcinoma triggered by IL11 paracrine signaling, thus resulting in chemoresistance." (PMID 33080792, 2020). "Future studies should focus on elucidating Stat3’s activating mechanism and its effects on downstream targets and on exploring the function of BBI608 in controlling relapse and metastasis of ovarian cancer because this compound could be vital in the clinic." (PMID 31778258, 2020). "In addition, our results suggest that Jagged1/Notch and JAK/STAT3 signalling form a positive regulatory loop and cooperatively regulates EMT and promote cisplatin‐resistant ovarian cancer cell invasion and migration." (PMID 30993885, 2019). "Other studies showed that phospho-STAT3 triggered abnormal dimerization of STAT3, increased the expression of anti-apoptotic proteins Bcl2, Bcl-xl, and MMP2/9, and promoted proliferation, survival, and migration/invasion in ovarian cancer, liver cancer and retinoblastoma cells." (PMID 31422383, 2019). "Further studies have identified that FEZF1-AS1 activated the Janus Kinase (JAK)-signal transducer and activator of transcription 3 (STAT3) signaling pathway by regulating the phosphorylation of STAT3, promoting the proliferation of ovarian cancer cells and inhibiting apoptosis." (PMID 31175144, 2019). "We previously reported that downregulation of the IL-6R/STAT3 signaling pathway did not affect total STAT3 expression in three ovarian cancer cell lines, as consistent with this study." (PMID 31448054, 2019). "Thus, our study demonstrated that STAT3 can modulate the expression of STAT5, and it is possible that STAT3 compensates for STAT5 signaling in ovarian cancer." (PMID 31534498, 2019). "Importantly, we demonstrated that STAT3 plays a critical role in cell-cycle progression, EMT, invasion, and maintenance of stemness in ovarian cancer in several model systems." (PMID 31534498, 2019). "Inhibiting STAT3 signaling reduces tumor progression, metastasis and chemoresistance, however the precise molecular mechanism has not been fully delineated in ovarian cancer." (PMID 31534498, 2019).
ovarian carcinoma (continued). "Knockdown of p110α expression alone or in combination with IL-6/STAT3 inhibition did not reduce ovarian cancer cell resistance to carboplatin induced by ascites medium." (PMID 29930760, 2018). "To test whether endogenous STAT3 localized to lysosomes in other cell types, we generated SKOV3 ovarian carcinoma cells with enhanced green fluorescent protein (EGFP) fused to the NH2 terminus of the endogenous STAT3 gene using CRISPR-Cas9 gene editing." (PMID 30127373, 2018). "Mechanistically, CT exerted its anti‐tumor effect by targeting STAT3/SIRT3/HIF‐1α signaling pathway in vitro and in vivo, which could be rescued by the introduction of SIRT3 shRNA in ovarian cancer cells." (PMID 30094960, 2018). "In addition to the in vitro studies, we also demonstrate that paclitaxel treatment significantly enhanced the activation of the JAK2/STAT3 pathway and CSC-like phenotype in the xenografts of mice injected with a serous human ovarian cancer HEY cell line." (PMID 29682172, 2018). "In the present study, we tested whether STAT3, phosphorylated at Tyr705, functions as a transcriptional activator, for positive regulation of MMP-9 in epithelial ovarian cancer." (PMID 28859117, 2017). "Leptin stimulation led to increased proliferation, survival and migration of LEPR-expressing ovarian cancer cell lines, with the effects shown to be mediated by the downstream Janus kinase 2/Signal transducer and activator of transcription 3 (JAK2/STAT3) pathway." (PMID 29212170, 2017). "Besides NID1, several regulators, such as HPIP, NANOG and FOXM1, have been reported to promote EMT of ovarian cancer cells and then confer them drug resistance, involving PI3K/AKT pathway, STAT3 pathway, etc." (PMID 28416770, 2017). "Western blot showed that miR-519d transfection in ovarian carcinoma cells downregulated RhoC (Ras homolog gene family member C), Bcl-2, cyclin D1, survivin, MMP2, MMP9, STAT3 (signal transducer and activator of transcription 3), and HuR (ELAV-like RNA-binding protein 1) expression (P < 0.05)." (PMID 28146423, 2017). "In agreement with the hypothesis of a CD24/STAT3 interplay in ovarian cancer stemness, CD24+ OCSC exhibit increased levels of STAT3 phosphorylation and of STAT3-dependent expression of stemness factors such as Nanog and c-Myc." (PMID 28320418, 2017). "In ovarian cancer cells, blockage of JAK/STAT3 signaling pathway hammers out the CSC traits." (PMID 27521216, 2016). "Survivin, c-Myc and Bcl-2 play active roles in cell proliferation and maintenance of ovarian cancers and are known as the common target genes of Wnt, Notch and STAT3 signaling." (PMID 25896424, 2015). "To further understand whether inhibition of the JAK/STAT3 pathway could increase the sensitivity of human ovarian cancer cells to gefitinib, we tested whether gefitinib sensitivity could be enhanced by siRNA-mediated knockdown of JAK or STAT3." (PMID 25928246, 2015). "In ovarian cancer cells, EGF binds to the EGF receptor (EGFR), thus inducing EMT activation through phosphorylation of the Janus kinase/signal transducer and activator of transcription (JAK/STAT3) pathway." (PMID 26356073, 2015). "In addition, we show that S1PR1, a regulator of STAT3 transcription via the JAK/STAT pathway, is highly expressed in hypoxic ovarian cancer cells (HOCCs)." (PMID 25594014, 2014). "EGFR and IL-6R signaling cross-talk through JAK2/STAT3 to mediate EMT in ovarian carcinomas; activated STAT3 in high-grade ovarian carcinomas may occur directly through activation of EGFR/IL-6R or indirectly through induction of IL-6R signaling." (PMID 25566498, 2014). "Although several studies have identified STAT3 as a focus of therapeutic intervention, the specific targeting of STAT3 Tyr705 in hypoxic ovarian cancer has not been investigated." (PMID 25594014, 2014).